IL18 (interleukin 18)
Diseases named in the same sentence as IL18 in open-access papers (continued):
Sharing a sentence is not in itself a finding about the gene and the disease.
post-traumatic stress disorder (2 papers, 2023 to 2025). An anxiety disorder precipitated by an experience of intense fear or horror while exposed to a traumatic (especially life-threatening) event. "Here, we used our established rat model of comorbid post-traumatic stress disorder (PTSD)/AUD to characterize the interleukin 18 (IL-18) system in the central amygdala (CeA)." (PMID 37566022, 2023). "The results of the conducted study provide significant evidence for the existence of associations between endoplasmic reticulum stress biomarkers (pPERK, IRE1α, ATF6) and the pro-inflammatory cytokine IL-18 with emotional regulation strategies in patients with post-traumatic stress disorder." (PMID 40806635, 2025).
Primary glaucoma (2 papers, 2022 to 2023). "Further investigation is needed to determine the pathophysiology of increased TNFα and IL-18 in primary glaucoma eyes." (PMID 35998207, 2022). "Primary glaucomatous eyes had the highest levels of IL-18 and TNFα which may indicate that inflammation plays a role in the pathogenesis of primary glaucoma in dogs." (PMID 35998207, 2022).
primary sclerosing cholangitis (2 papers, 2024 to 2026). "The potential relevance of some genes in IBD has been supported by previous studies, such as RETN with increased resistin levels in CD and primary sclerosing cholangitis, the FLT3 receptor in a mouse model of chronic ileitis, and the therapeutic potential of IL-18 inhibition." (PMID 39165421, 2024). "The discordant direction in primary sclerosing cholangitis may reflect distinct cholangiocyte contexts that are rich in inflammasome and interleukin 18 pathways, but direct evidence is still lacking." (PMID 41442179, 2026).
prostate tumor (2 papers, 2017 to 2021). "We tested single or sequential IL-27 and IL-18 therapies both in cells and in vivo, finding significant promise for the sequential 27→18 method for prostate tumors." (PMID 34209203, 2021). "Identifying such factors leading to inflammasome activation and maturation of IL-1β and IL-18 will help in understanding the role of inflammation in the prostate tumor microenvironment." (PMID 28663562, 2017). "We therefore hypothesized that the efficacy of our IL-27 gene delivery protocol for prostate tumors could be augmented if combined with IL-18 administration, especially if administered sequentially." (PMID 34209203, 2021). "The IL-18 was given as a recombinant cytokine (rIL-18) intratumorally, based on a previous study where it could yield partial antitumor responses when administered directly to prostate tumors." (PMID 34209203, 2021).
Psoriasiform dermatitis (2 papers, 2021 to 2025). A skin abnormality characterized by redness and irritation, with thick, red skin that displays flaky, silver-white patches (scales). "HMGB1, and subsequently IL-18, determined the development of psoriasiform dermatitis in the imiquimod-treated mouse model." (PMID 35053208, 2021).
renal carcinoma (2 papers, 2021 to 2023). A carcinoma arising from the epithelium of the renal parenchyma or the renal pelvis. "As control we investigated on the NLRP3 expression and production of IL-1β and IL-18 by cardiac cells and renal cancer cells during exposure to sunitinib alone or combined to resveratrol." (PMID 34178667, 2021).
retinal disease (2 papers, 2019 to 2025). "Importantly, MCMV-infected eyes of MAIDS-10 mice deficient in either caspase-1, GSDMD, or IL-18 all consistently showed a pattern of retinal disease similar, if not identical, to that observed in the present study for MAIDS-10 mice deficient in the NLRP3, NLRP1b, or AIM2 inflammasomes." (PMID 41011779, 2025).
retinal ischemia (2 papers, 2018 to 2020). A ischemic disease that involves the retina. "MIP-1β, TNF-α and IL-18 are proinflammatory factors that can compromise the blood–retinal barrier, exacerbate retinal ischemia, modulate angiogenesis, and induce the progression of ROP." (PMID 32728160, 2020).
rhabdomyolysis (2 papers, 2012 to 2015). Necrosis or disintegration of skeletal muscle often followed by myoglobinuria. "We describe a case of rhabdomyolysis in a patient infected with antimicrobial drug–resistant Mycoplasma pneumoniae The patient’s acute-phase serum levels of interleukin-18 and tumor necrosis factor–α were high, which suggests a pathogenic role for M. pneumoniae." (PMID 22515975, 2012). "We also analyzed the relationships between urinary KIM-1 and IL-18 and the age, TBSA, TDBA, presence of rhabdomyolysis, and APACHE II scores of burn patients." (PMID 26283194, 2015).
schistosomiasis (2 papers, 2014 to 2023). An infectious disease caused by parasitic trematodes of the genus Schistosoma that colonize human blood vessels and release eggs that can cause granulomatous reactions leading to acute (swimmer's itch or acute schistosomiasis syndrome) or chronic disease. "The Th1/Th2 cytokines in chronic patients were not significantly different from those in healthy people, while patients with advanced schistosomiasis had higher levels of IL-2, IL-23 and IL-27 and lower levels of IL-18 and IFN-γ." (PMID 37887717, 2023). "In addition, patients with advanced schistosomiasis had lower IL-18 and IFN-γ levels than those with chronic schistosomiasis and the healthy controls." (PMID 37887717, 2023). "IL-18 induces IFN-γ together with IL-12 or IL-15 and plays a role similar to IFN-γ, which is supported by our results showing that the expression of IFN-γ and IL-18 in late-staged schistosomiasis patients was significantly lower than that in chronic patients and healthy people." (PMID 37887717, 2023). "In summary, we found significantly lower levels of IL-18 and IFN-γ and higher levels of IL-23 in patients with advanced schistosomiasis compared with healthy controls and chronic patients." (PMID 37887717, 2023).
scleroderma (2 papers, 2019 to 2022). Scleroderma is a rare autoimmune connective tissue disorder characterized by abnormal hardening of the skin and, sometimes, other organs. "Interestingly, we found that the expression of GSDMD, caspase-1, IL-1β, and IL-18 increased significantly at the early stage (days 7 and 14) of the disease in scleroderma mice." (PMID 35396386, 2022).
scrub typhus (2 papers, 2016 to 2017). Scrub typhus is a rare dust mite-borne infectious disease caused by the Orientia tsutsugamushi bacterium and characterized clinically by an eruptive fever which is potentially serious. "The notion is supported by our observation that plasma levels of IL-12 and IL-18 were increased in scrub typhus patients and that addition of IL-12 and IL-18 upregulated CD69 expression in NK cells." (PMID 28750012, 2017). "To investigate the expression of these cytokines in NK cells, we incubated PBMCs obtained from five patients with scrub typhus and 10 HCs for 24 hours in the presence of IL-12 and IL-18." (PMID 28750012, 2017). "Based on our observation that IFN-γ-inducing cytokines were increased in scrub typhus patients, we next examined whether NK cells might be activated after stimulation with IL-12 and IL-18." (PMID 28750012, 2017). "Furthermore, a previous study showed that plasma IL-12p40 and IL-18 levels were elevated in scrub typhus patients." (PMID 27463223, 2016). "In scrub typhus patients, tests showed their NK cells produced higher amounts of interferon (IFN)-γ after stimulation with interleukin (IL)-12 and IL-18 relative to those of HCs." (PMID 28750012, 2017). "Next, we measured plasma levels of IFN-γ, IL-17, and IFN-γ-inducing cytokines, such as IL-12, IL-18 and TNF-α, in 25 patients with scrub typhus and 15 age- and sex-matched HCs using Luminex assay and ELISA." (PMID 28750012, 2017). "Collectively, these findings suggest that MAIT cells can be activated by IL-12 and IL-18, in an MR1-independent manner, in scrub typhus." (PMID 27463223, 2016). "Moreover, the plasma levels of IFN-γ, IL-12, IL-18 and TNF-α were significantly higher in scrub typhus patients than in HCs." (PMID 28750012, 2017).
Sézary syndrome (2 papers, 2023 to 2024). "Of note for Sézary syndrome, there are discrepancies in the expression of IL-18 in serum and tissues or even in different parts of the same tissue." (PMID 38397043, 2024). "Increased serum levels of IL-18 were also detected in Sézary syndrome patients, while the LNs of patients with advanced-stage disease showed an upregulation of IL-18 and downregulation of IL-1β." (PMID 38397043, 2024). "The findings indicated an aberrant IL-18 expression in the skin and at circulating levels in Sézary syndrome." (PMID 36902104, 2023). "Overall, the present findings showed compartmentalized expressions of IL-1B and IL-18 and provided the first evidence of their imbalance in patients with Sézary syndrome." (PMID 36902104, 2023). "However, in the dermal layer, IL-18 showed increased expression in Sézary syndrome patients, while IL-1β levels were comparable among patients and controls." (PMID 38397043, 2024). "Herein, to verify whether the expression of inflammasome components could be altered by Sézary syndrome, we assessed the expression of NLRP1, NLRP3, AIM2, IL-1B and IL-18 by immunohistochemistry in the epidermal and dermal layers of skin from SS patients." (PMID 36902104, 2023).
skin infection (2 papers, 2020 to 2023). An inflammatory process affecting the skin, caused by bacteria, viruses, parasites, or fungi. "However, since IL-18 expression is elevated in experimental murine infections, we decided to examine whether IL-18 activation by SpeB could provide protective benefit in the typical skin infection model." (PMID 37068092, 2023).
thymoma (2 papers, 2010 to 2025). A neoplasm arising from the epithelial cells of the thymus. "IL-18 levels were significantly higher in patients with thymic carcinoma, while thymoma patients displayed lower levels." (PMID 41368637, 2025). "When bound to the IL-18R, IL-18 induces the formation of an IL-1R-associated kinase (IRAK)/TNF receptor-associated factor-6 (TRAF-6), a multipart structure that has stimulatory activity for nuclear factor κB (NF-κB) in Th1 cells and in EL4/6.1 thymoma cells." (PMID 20565717, 2010).
tonsillitis (2 papers, 2021 to 2024). Inflammation of the tonsillar tissue. "In addition, we will also examine the relevant pathways in order to explain the association of increased levels of IL-1ß, IL-18 and S100A8/A9 in patients suffering from recurrent tonsillitis." (PMID 34187480, 2021). "Elevated levels of IL-18, S100A8/A9 specifically in serum and IL-1β in saliva can be used as a novel, objective biomarkers and collectively scored using the RAT-score to identify patients with recurrent tonsillitis." (PMID 34187480, 2021).
unstable angina pectoris (2 papers, 2014 to 2024). "Additional studies from an Isreal cohort and a Chinese cohort reported elevated IL-18 levels in patients with stable angina pectoris (SAP) and unstable angina pectoris (UAP) than in healthy or CAD-free controls." (PMID 39766338, 2024).
urolithiasis (2 papers, 2023). Stone(s) within the urinary tract. "However, previous reports have focused on the frequency of polymorphisms located in IL-1RN, IL-1β, and IL-18 genes in patients with urolithiasis." (PMID 37878647, 2023). "However, there was no causal association between other common risk factors (PTH, CRP, IL6, IL18, IL27, IL8, IL16, IL1Ra, coffee consumption, age of smoking initiation, smoking initiation, and cigarettes smoked per day) and urolithiasis in the meta-analysis." (PMID 37624788, 2023).
Vaginal infection (2 papers, 2016 to 2019). "Vaginal infection in a mouse model of HSV-2 demonstrated that Il18−/− mice died sooner than WT mice and viral titers were higher in Il18−/− mice on day 3 after infection." (PMID 27592079, 2016). "Of note, the phenotype of Il18−/− mice strongly resembles that observed in Il22−/− mice, further pointing to the collaborative IL-18 and IL-22 cross-talk in protection against Candida vaginal infection." (PMID 31681274, 2019).
vascular dementia (2 papers, 2016 to 2025). A degenerative vascular disorder affecting the brain. "Moreover, it exacerbates vascular dementia by producing IL-18, IL-1β, and the N-terminal fragment of GSDMD, which also contributes to neuronal cell death." (PMID 40326096, 2025).
Ventricular arrhythmia (2 papers, 2024 to 2025). "In the future, the expression of ASC, caspase-1 and IL-18 in the myocardium of ventricular arrhythmia rats will continue to increase, providing a theoretical basis for the resistance of cinnamaldehyde against myocardial inflammatory injury." (PMID 40146271, 2025).
ventricular tachycardia (2 papers, 2023). A disorder characterized by an electrocardiographic finding of three or more consecutive complexes of ventricular origin with a rate greater than a certain threshold (100 or 120 beats per minute are commonly used). "Notably, continued IL-18 suppression by IL-18-binding protein leads to cardiac fibrosis reduction and NF-κB phosphorylation, diastolic function improvement, electrical remodeling normalization, and IL-18-mediated ventricular tachycardia reduction in mice." (PMID 35997998, 2023).
viral pneumonia (2 papers, 2020 to 2023). Inflammation of the lung parenchyma that is caused by a viral infection. "However, based on the predictive modeling, IL-15 and IL-18 in combination with the metabolome and microbiome data may be more useful for distinguishing bacterial vs viral pneumonias." (PMID 32770049, 2020).
vitamin D deficiency (2 papers, 2021 to 2023). A nutritional condition produced by a deficiency of VITAMIN D in the diet, insufficient production of vitamin D in the skin, inadequate absorption of vitamin D from the diet, or abnormal conversion of vitamin D to its bioactive metabolites. "For example, vitamin D deficiency may enhance inflammation, chemokine production via NF-ƘB, parenchymal degradation, TNF-α, IL-18, histone acetylation, corticosteroid resistance, and matrix metalloproteinase (MMP)-9 production." (PMID 37006939, 2023).
abnormal glucose tolerance (1 paper, 2021). "It has been demonstrated that the increased level of blood glucose promotes a sharp increase in the concentrations of inflammatory cytokines, such as interleukin-6, tumor necrosis factor α, and interleukin-18, and this effect was more pronounced in subjects with abnormal glucose tolerance." (PMID 35059413, 2021).
abscesses (1 paper, 2025). "By inhibiting GSDMD, it may be possible to reduce the release of IL-1β and IL-18, thereby dampening the inflammatory response and preventing the progression of lesions into chronic, scarring abscesses and tunnels." (PMID 41007405, 2025).
Achalasia (1 paper, 2024). A disorder of esophageal motility characterized by the inability of the lower esophageal sphincter to relax during swallowing and by inadequate or lacking peristalsis in the lower half of the body of the esophagus. "Patients with achalasia exhibited increased concentrations of eleven cytokines and chemokines, namely TGF-ß1, TGF-ß2, TGF-ß3, IL-1ra, IL-17, IL-18, IFN-γ, MIG, PDGF-BB, IP-10 and SCGF-B." (PMID 39337632, 2024). "Moreover, twelve biomarkers were significantly increased in type III compared with I and II achalasia, namely, TGF-ß2, IL-1ra, IL-2Ra, IL-18, MIG, IFN-γ, SDF-1a, Eotaxin, PDGF-BB, IP-10, MCP-1 and TRAIL." (PMID 39337632, 2024).
Acute Aortic Dissection (1 paper, 2019). "This study is aimed at determining whether IL-18 is related to aortic dissection (AD) and identifying the underlying mechanisms." (PMID 31427887, 2019). "In an earlier study of IL-18, it was reported that granulocyte macrophage colony-stimulating factor (GM-CSF) is a key regulatory and molecular causative agent of aortic dissection/intramural hematoma in a murine model of this condition and is also related to this condition in humans." (PMID 31427887, 2019).
acute inflammatory demyelinating polyneuropathy (1 paper, 2026). "Isolated reports also indicate a role for IL-18 in the pathogenesis of inflammatory demyelinating neuropathies." (PMID 41602156, 2026). "It has been detected in human inflammatory neuropathies: IL-18 expression is induced in acute inflammatory demyelinating polyneuropathy, and serum levels rise in immune neuromuscular conditions, highlighting the cytokine’s proximity to peripheral nerve inflammation." (PMID 41602156, 2026).
acute pharyngitis (1 paper, 2022). An acute and painful inflammatory process that affects the pharynx. "The hallmarks of acute pharyngitis are increased levels of monocyte and dendritic cell subsets, elevation of IL-1Ra, IP-10 and IL-18, activation of unconventional T cells, and migration of B cells and CD4+ T-cell subsets from the blood." (PMID 35140232, 2022).
adult onset asthma (1 paper, 2023). "In this Mendelian Randomization (MR) study, we utilized extensive summary data from Genome-Wide Association Studies (GWAS) to further estimate the association between adult-onset asthma and the risk of UC, and to investigate the role of Interleukin-18 (IL-18) as a potential mediator." (PMID 38162651, 2023).
alcoholic cirrhosis (1 paper, 2021). "The MAIT cells in patients with alcoholic cirrhosis were prone to apoptosis, which was promoted by IL-12, IL-18, and IL-8." (PMID 34321090, 2021).
alcoholic fatty liver disease (1 paper, 2023). Lipid infiltration of the hepatic parenchymal cells that is due to alcohol abuse. "Last, IL-18 has been identified to correlate positively with the severity of PBC in patients, was tendentially increased in patients with PSC32 and has been shown to increase the risk of liver injury in a non-alcoholic fatty liver disease mouse model." (PMID 37841639, 2023).
anterior uveitis (1 paper, 2022). Inflammation of the iris and anterior chamber of the eye. "The current study demonstrates that IL-4, IL-6, IL-18, and TNFα have the potential to be relevant in dogs with post-phaco anterior uveitis." (PMID 35998207, 2022). "Our study is consistent with the human literature regarding IL-18 involvement in anterior uveitis post-phaco." (PMID 35998207, 2022). "Also, IL-4, IL-6, IL-18, and TNFα may be important pro-inflammatory cytokines in dogs with anterior uveitis and POH following phacoemulsification (‘POH group’)." (PMID 35998207, 2022). "Dogs with anterior uveitis and POH following phacoemulsification surgery express elevated levels of IL-4, IL-6, IL-18 and TNFα in AH, which is consistent with the human literature." (PMID 35998207, 2022). "Conversely, IL-18 was positively correlated with IOP which could indicate that increasing IL-18 is a response to a rise in IOP rather than the anterior uveitis." (PMID 35998207, 2022).
aortic aneurysm (1 paper, 2023). A ruptured aneurysm located in the wall of the proximal portion of the descending aorta proceeding from the arch of the aorta. "IL-18 and P-selectin may also have a potential effect on the development of aortic aneurysms, given that gene deletions of IL-18 and P-selectin attenuate the formation of aortic aneurysms in animals, probably by mitigation of the inflammatory response." (PMID 35996028, 2023).
atrophic gastritis (1 paper, 2024). "Consequently, CagA-induced proinflammatory cytokines, interleukin (IL)-1, IL-6, IL-18, tumor necrosis factor α (TNFα), and interferon-γ (IFN-γ), will increase, triggering gastric mucosa inflammation and atrophic gastritis." (PMID 38276136, 2024).
autoimmune hyperthyroidism (1 paper, 2021). "Cytokines are elevated in autoimmune (i.e., IL-18, IL-6) and non-autoimmune hyperthyroidism (i.e., TNF-α, IL-8, IL-6), and this could be associated with the chronic effects of thyroid hormone increase." (PMID 33935970, 2021).
Azoospermia (1 paper, 2024). Absence of any measurable level of sperm,whereby spermatozoa cannot be observed even after centrifugation of the semen pellet. "The alignment of gene expression results from tissue and blood samples, coupled with ROC curve analysis, suggests that investigating AIM-2, NLRC-4/IPAF, and IL-18 could serve as three potential biomarkers for predicting and differentiating the causes of azoospermia." (PMID 39712014, 2024).